WNT7A (Wnt family member 7A)
Diseases named in the same sentence as WNT7A in open-access papers (continued):
Sharing a sentence is not in itself a finding about the gene and the disease.
cancer (60 papers, 2009 to 2025). A tumor composed of atypical neoplastic, often pleomorphic cells that invade other tissues. "In epithelial ovarian cancer, activated STAT4 is overexpressed and promotes cancer metastasis via tumor-derived Wnt7a-induced activation of cancer-associated fibroblasts." (PMID 38611065, 2024). "E-cadherin loss was closely related to the poor prognosis and survival of many cancers, suggesting that promoter methylation-induced WNT7A loss might be an important prognostic factor in NSCLC." (PMID 35957916, 2022). "The existing research data about the association of WNT7A with cancers are inconsistent." (PMID 32174831, 2020). "It is possible that cancer cell‐derived factors Wnt7a and osteopontin, which were proposed to mediate fibroblast activation to CAFs, are involved in these processes." (PMID 39887653, 2025). "mRNA expression of FAM83A, LY6D, MET, MUC16, MYEOV, and WNT7A were significantly elevated in cancer than healthy tissues (P<0.05)." (PMID 38169540, 2024). "Conversely, the cancer cell–derived WNT7A, WNT7B, and WNT10A and stromal WNT3 and WNT9A were highly expressed in the squamous subtype." (PMID 35536676, 2022). "This contradiction suggested that the role of WNT7A in tumorigenesis was type-dependent and that investigation of its role in more cancers was needed." (PMID 32174831, 2020). "And we found Wnt7a protein permeated at cytoplasm with a decreased signal in cancer tissues compared to paracarcinoma tissues in 21 specimens." (PMID 31886205, 2019). "Previous studies have demonstrated that the aberrant expression of Wnt7a exists in a variety of cancers." (PMID 31886205, 2019). "Then, we performed transwell assays and wound healing assays in vitro and found that WNT7A promotes the migration capacity of cancer cells." (PMID 30361522, 2018). "Signal transduction genes (i.e., ADCY4/7/8/9,) are also in the list of our 102 genes, which also includes cancer stem cell signaling genes (i.e., WNT7A, GLI1/2/3, NOTCH2/3/4, ALDH1A3)." (PMID 29304754, 2018). "CXCL1, MMP9, IL1B, WNT7A, and CCL2 were associated with cancer malignant characteristics which were remarkably decreased in Top 10 list." (PMID 28881805, 2017). "Wnt7a is frequently lost in a subset of NSCLC, and restoration of Wnt7a expression in the context of Fzd9 results in increased differentiation and decreased transformed phenotype in cancer cell lines." (PMID 23862015, 2013). "The strategy was to transiently express either Wnt3 or Wnt7a in A549 cells, isolate total RNA, and screen for miRNA expression by using a cancer-specific miRNA super-array." (PMID 23862015, 2013). "In macrophages grown as co-culture with cancer cells expression of three ligands of Wnt pathway increased significantly: Wnt5b, Wnt7a and Wnt7b." (PMID 22353646, 2012). "Further, we found Wnt-7a (wingless-type MMTV integration site family, member 7A; located at 3p25) to be more expressed in EnA samples compared to EnD cancers." (PMID 22040021, 2011). "Furthermore, low levels of let-7a-5p miRNA and high levels of FZD4, WNT7A, and b-Catenin genes were correlated with worse cancer-specific survival." (PMID 38396855, 2024). "Interestingly, WNT7a gene is located at the chromosome 3p25 region, which is known as a predilection site of homozygous deletion of many anti-cancer genes." (PMID 37486552, 2023). "Examination of DES cluster 5 for expression of Wnt signaling targets, however, indicated that relative to other DES clusters, the DES cancer cells had among the lowest expression of Wnt ligands, receptors, and target genes including Wnt7a, Ccnd2, Axin2, and Myc." (PMID 37856394, 2023). "With regard to cancer, WNT7a seems to have pleiotropic functions." (PMID 35885035, 2022). "PRDX6 may promote the occurrence and development of ICC by regulating Wnt7a/Mmp7 in cancer cells and Wnt7b/Ccnd2 in macrophages." (PMID 36209344, 2022). "Wnt7a is mainly expressed in cancer cells and Wnt7b is expressed in macrophages." (PMID 36209344, 2022).
cancer (continued). "In addition, Wnt pathway alterations were detected in many kinds of cancer, confirming its importance during bladder carcinogenesis; a finding compatible with our results that showed a significant elevation in WNT7A and CTNNB1 expression in high stages." (PMID 36140796, 2022). "Moreover, to reduce the ability of inhibiting autophagy, promoting proliferation and EMT by FGF2, and to inhibit the ability of promoting cancer cell metastasis by WNT7A, AKT1 was selected as a biomarker to be inhibited." (PMID 35743172, 2022). "A literature review revealed that Wnt7A is significantly expressed in various cancers 32-34." (PMID 35517414, 2022). "The results of this study clearly demonstrate a unique relationship between EGF signaling and WNT7A expression in regulating cancer cell migration, which could be essential in the identification of therapeutic targets for the treatment of OSCC." (PMID 32174831, 2020). "The effect of WNT7A on cancer development is type-dependent." (PMID 32174831, 2020). "In addition, WNT7A knockdown cancer cells show a significantly decreased growth rate and invasion ability in a xenografts model." (PMID 27259239, 2016). "The reason for selecting hsa-miR29b over other miRNAs is 2-fold: 1) hsa-miR29b was upregulated by more than 19-fold in A549 cells expressing Wnt7a in comparison to empty vector control, and 2) several studies have shown either a direct or an indirect role for hsa-miR29b in human cancers." (PMID 23862015, 2013). "Thus promoter hypermethylation acts as the main mechanism of the WNT7A silencing in a wide range of cancer types." (PMID 23056560, 2012). "The behavior of the WNT7A gene in human cancer is tissue-specific." (PMID 23056560, 2012). "Additionally, it was shown that inactivation of WNT7A through DNA hypermethylation stabilizes the cancer phenotype of OSCC cell lines." (PMID 23056560, 2012). "Notably, this included TGF-β (TGFB1, TGFB3), drivers of adenosine-mediated immune suppression (NT5E (CD73), ENTPD1 (CD39)), Wnt pathway ligands (WNT7A, WNT4), IL10 and drivers/markers of cancer-associated fibroblast activation (INHBA, WNT7A, TGFB1, FAP, PDGFRA, PDGFRB)." (PMID 39568014, 2024). "Interestingly, a recent study showed that expressing Wnt7a in muscle could suppress muscle wasting in a mouse model of cancer cachexia." (PMID 34078667, 2021). "Among the WNT ligands, WNT7A, WNT7B and WNT10A have the highest expression in cancer cells, and the largest increase in expression in bulk PDACs compared to normal pancreatic tissue." (PMID 38678032, 2024). "Our study further confirms that WNT7A is overexpressed in HNSCC, indicating its potential oncogenic role in this cancer as well." (PMID 38246919, 2024). "This cancer cell subpopulation also showed statistically significant elevated expression of WNT7B, WNT7A, WNT10A and WNT4 besides the CSC markers, compared to the rest of the PDAC cells." (PMID 38678032, 2024). "For instance, in the interconnection among predicted target mRNAs and multiple signaling pathways, WNT7A and FZD5 regulates “Wnt signaling pathway,” “Proteoglycans in cancer,” and “Pathways in cancer”." (PMID 34557357, 2021). "Since the expression of WNT7A is positively correlated with poor prognosis of PDAC cases, we determined to investigate the biological functions of WNT7A in cancer cell lines." (PMID 30361522, 2018). "Pathways in Cancer describe of 251/327 genes RAF1 and VHL again as G1 nominators followed by WNT7A (15/26) and MLH1 (22/26) with p<0.00553, respectively p<0.00985." (PMID 28486536, 2017). "Let-7a target gene (WNT7A, β-catenin, IRS2, and FZD4) expression significantly increased in T2–T4 compared with pT1 as let-7a miRNA inhibition stimulates FZD4 and Wnt/β-catenin pathway in cancer cells." (PMID 36140796, 2022). "When FZD9 binds to Wnt7a in the lung epithelium and initiates anti-cancer signaling through PPARγ, it does not activate canonical β-catenin signaling." (PMID 35924166, 2022).
cancer (continued). "Our results collectively indicate that NOMAC exhibits strong anti-cancer activity both in vitro and in vivo, and it might related to the upregulation of SUFU and Wnt7a." (PMID 28640224, 2017). "It is worth mentioning that in the existing studies, WNT7A and WNT2B played different roles in the prognosis of different cancer types, which may be attributed to their various mechanisms of action in diverse cancer cell lines and the activated signaling pathways." (PMID 35957916, 2022). "Sequencing results showed that Wnt7a, Wnt7b, Fzd2, Mmp7 and Ccnd2 in the Wnt signaling pathway were downregulated after PRDX6 knockout, suggesting that this signaling pathway may be involved in the regulation of PRDX6's cancer-promoting effect." (PMID 36209344, 2022). "Wnt7a activates both canonical and non-canonical Wnt signaling pathways via binding to its receptors, resulting in diverse consequences in different diseases and cancers." (PMID 36096830, 2022). "Considering that WNT7A could regulate cancer progression through canonical or non-canonical Wnt signaling, our subsequent studies were focused on the downstream signaling of WNT7A in response to EGF stimulation." (PMID 32174831, 2020).
infection (4 papers, 2012 to 2023). The state of being infected such as from the introduction of a foreign agent such as serum, vaccine, antigenic substance or organism. "Since Wnt7a has been shown to activate multiple signaling pathways, markers of these pathways were evaluated upon lenti-Wnt7a-GFP infection of human articular chondrocytes (nHACs)." (PMID 28165497, 2017). "After 48 h of infection, cells were cultured with 1 μg/mL puromycin for selection of infected cells, and RNA and protein extraction were conducted on day 7 to corroborate WNT7A overexpression by qRT-PCR and Western blot assays." (PMID 22313908, 2012). "In addition, through ex vivo infection of peripheral blood mononuclear cells (PBMCs) collected from healthy donors, SFTSV inhibited the transcription levels of WNT7A and WNT10B." (PMID 37882780, 2023). "Moreover, RECK regulates MMP9 and exerts its effects primarily through suppression of WNT7A/WNT7B, but regulation of neither Wnt7a nor Wnt7b regulation was observed in our gene microarray dataset, and scRNA-Seq did not detect Wnt7a nor Wnt7b expression, before or after infection, in any ME cells." (PMID 36092940, 2022).
adenocarcinoma (2 papers, 2015 to 2022). A common cancer characterized by the presence of malignant glandular cells. "WNT7A and WNT10A may contribute to female reproductive system adenocarcinomas, while LRP5 prefer adenocarcinomas of digestive organs." (PMID 35850748, 2022).
benign tumors (1 paper, 2009). "Differential expression was also observed between LMP tumors and benign tumors/normal ovaries for three out of five genes examined (PDGFRA, SLPI, WNT7A) and between invasive and LMP tumors for the other two genes (C6orf31, GLTSCR2) (Kruskal Wallis p < 0.05)." (PMID 19849863, 2009).
brain diseases (1 paper, 2024). "Among the genes annotated to SOX2-bound elements, numerous have been associated with astrogliosis and reactive astrocyte proliferation after TBI or other brain diseases, such as Nr2e1, Mmd2, Wnt7a, and Akt2." (PMID 38672150, 2024).
gynecologic diseases (1 paper, 2012). "Studies have correlated sex hormones with Wnt7a expression in gynecologic diseases." (PMID 23304155, 2012).
hematological disorders (1 paper, 2012). "One of the first observations of the implication of WNT7A in hematological disorders was the frequent deletion of the 3p25 chromosome band observed in patients with AML, CML, and ALL." (PMID 22313908, 2012). "On the other hand, expression of WNT7A in hematological diseases has been only determined in patients with CLL and AML." (PMID 22313908, 2012).
neuromuscular disease (1 paper, 2024). "Our experiments suggest that systemic delivery of Wnt7a loaded on EVs represents a potential therapy for treating neuromuscular diseases." (PMID 39661666, 2024). "We therefore set out to determine whether Wnt7a is secreted on EVs and to decipher the mechanism by which Wnt7a is loaded onto EVs to provide insight into long-range Wnt signaling for the treatment of neuromuscular diseases." (PMID 39661666, 2024).
WNT7A also shares sentences with these, for which no sentence is quoted: Fuhrmann syndrome (3 papers); glioblastoma (3); oral squamous cell carcinoma (3); cholestasis (2); osteosarcoma (2); pulmonary fibrosis (2); ulcerative colitis (2); adenoma (1); autism spectrum disorder (1); benign ovarian tumours (1); brain cancer (1); brain tumors (1); Cerebral ischemia (1); chronic lymphocytic leukemia (1); Chronic myeloid leukemia (1); CNS tumor (1); colorectal adenoma (1); craniosynostosis (1); endometriosis (1); hyperplastic (1); Intellectual disability (1); ischemic stroke (1); liver disease (1); male infertility (1); malignant pleural mesothelioma (1); myopathy (1); Nail dysplasia (1); papillary thyroid cancer (1); Phocomelia (1); polydactyly (1).
A further 13 diseases each share a sentence with WNT7A in 1 paper.